ALB (albumin)
Diseases named in the same sentence as ALB in open-access papers (continued):
Sharing a sentence is not in itself a finding about the gene and the disease.
Ascites (continued). "The CTP class 0 was defined by fulfilling all criteria of albumin ≧4 g/dL, bilirubin ≦0.8 mg/dL, prothrombin time prolongation <0 seconds, no ascites and encephalopathy." (PMID 24906132, 2014). "The new CTP class 0 were defined by fulfilling all the criteria of serum albumin ≧4.0 g/dL, bilirubin ≤0.8 mg/dL, PT prolongation <0 second, no ascites and no encephalopathy." (PMID 24906132, 2014). "For example, in a patient with refractory ascites, a MELD score of 10, a serum sodium concentration of 125 mmol/L, and a serum albumin concentration of 2.0 g/dL, the MELDNa score would be 21 and 5vMELD score would be 26 (differences from MELD of 11 and 16 points, respectively)." (PMID 23349678, 2013). "The nutritional status estimated by the BMI was a predictor of HRQOL, independent of the presence of ascites or low albumin." (PMID 24490061, 2013). "The albumin, prothrombin time, urea and creatinine were in the normal range and neither group demonstrated any ascites or hepatic encephalopaghy, indicating that none of the patients in the two groups had renal or hepatic dysfunction." (PMID 24147111, 2013). "Indeed, in this patient, the Child-Pugh class was C, showing poor liver function, and the albumin levels at the time-points of BRTO and ascites evaluation by CT were 2.1 (g/dL) and 2.0 (g/dL), respectively." (PMID 23304539, 2012). "However, in general, albumin levels have been reported to decrease one month after BRTO and it is unlikely that improvement of ascites within 2 weeks after BRTO, as was observed in this patient, would have been due to improvement of the serum albumin levels." (PMID 23304539, 2012). "Calculation of a Child-Pugh score is done by assessment of serum bilirubin level, serum albumin level, prothrombin time, presence or absence of ascites, and hepatic encephalopathy." (PMID 21129071, 2010). "The current standard of care for the treatment of clinically relevant ascites relies on the combination of diuretics (both aldosterone antagonists and loop diuretics) and periodic large-volume paracentesis (LVP) when needed, followed by albumin administration according to international guidelines." (PMID 38592162, 2024). "The results demonstrated that the proportion of patients with no prior abdominopelvic surgery was higher, the serum albumin level was lower, and the proportion of patients in which ascites were detected by ultrasonography was higher in group 2 than that in group 1." (PMID 36896265, 2023). "However, the C–P class includes clinical, non-standardized parameters (ascites and encephalopathy) and mutually related factors (serum albumin and ascites) and has no statistical foundation." (PMID 36836588, 2023). "As regards the association between lung volumes and the severity of liver cirrhosis and clinicolaboratory characteristics, TLC has been shown to exhibit a significant positive correlation with serum albumin levels and a significant negative correlation with the presence of ascites." (PMID 37533800, 2023). "In addition, DLCO has been found to exhibit a significant positive correlation with serum albumin and cholinesterase levels, and a significant negative correlation with esophageal varices and ascites." (PMID 37533800, 2023). "Serum albumin less than 1.1 g/dL, hyperglobulinemia, arterial hypotension/shock, and even long-standing congestive heart failure, as illustrated in the case, may result in unexpectedly low SAAG ascites." (PMID 35178310, 2022). "Besides laboratory function (albumin, bilirubin and ALBI score), imaging signs of decreased liver function, such as varices, ascites, pleural effusion and hepatocellular uptake of hepatobiliary contrast media (as described by LSR and RLE) were also predictors of OS in our study." (PMID 34686780, 2022). "Some beneficial effects of commercial albumin infusions have been observed in patients with liver cirrhosis and subsequent ascites, in the context of other diseases this effect could not be clearly demonstrated." (PMID 35842435, 2022).
Ascites (continued). "However, the Child-Pugh system includes subjective (due to grade of ascites and hepatic encephalopathy) and interrelated (i.e., albumin and ascites) components, and has no weighting scores on each component." (PMID 32487089, 2020). "The only trial with no deaths assessed hyperoncotic albumin in the treatment of ascites." (PMID 21029460, 2010). "This study aimed to determine whether intravenous albumin treatment extends the interval between paracentesis procedures, while also preventing paracentesis-induced circulatory dysfunction (PICD) and renal dysfunction among cirrhotic patients who experience recurrent ascites." (PMID 40662011, 2025). "Additionally, repeated large volume paracentesis plus albumin (8 g/L of ascites removed) may be required for refractory ascites, and the use of nonselective beta-blockers should be cautious in severe or refractory ascites." (PMID 31234316, 2019). "Moreover, a protein nutrition status might have an impact on ascites formation in both sexes, although we could not confirm significant differences in peripheral blood albumin levels." (PMID 26107937, 2015). "However, albumin does not interfere with the main mechanisms of ascites formation and therefore only prevents complications of paracentesis rather than prevents the recurrence of ascites." (PMID 24467993, 2014). "Liver function according to the levels of bilirubin, albumin, INR, MELD-Na, and CTP class was significantly better in patients without ascites." (PMID 40004608, 2025). "Baseline ascites did not have a significant effect on GFR, yet there was a trend towards significance for baseline albumin." (PMID 40444235, 2025). "Patients prescribed NSBBs at baseline had similar age, gender, presence of ascites, MELD score serum albumin and CRP to those not, but significantly increased incidence of suspected variceal bleeds and serum creatinine and significantly reduced WCC." (PMID 36407574, 2023). "A total of 5 out of the 65 cats had both pleural and peritoneal effusion collected as a part of the previous investigation; however, only ascites was included in the present study due to the lack of LDH and albumin measurement in all five pleural effusions." (PMID 37370428, 2023). "One of the important features of heart failure-related ascites is high gradient ascites (SAAG >1.1 g/dL); however, low gradient ascites is not uncommon in patients with long-standing heart failure, especially those with low serum albumin values." (PMID 35178310, 2022). "We then carried out a GWAS on the five above-mentioned schistosomiasis-related clinical symptoms (HA, AST, albumin, PVD, and ascites grade) among 637 non-related individuals after excluding 263 related subjects." (PMID 35493725, 2022). "AOPPs-albumin levels were significantly different between nonascites and CHC patients with ascites (n = 53; median 3.6 μmol/g, IQR 1.9–5.2 μmol/g)." (PMID 26665009, 2015). "The factors we selected based on admission variables were similar to those reported by other researchers (e.g., bilirubin, serum albumin, INR, serum sodium level, mDF, CPT, MELD, MELD-Na, ascites, encephalopathy, and the CS nonresponse)." (PMID 24151614, 2013). "Other covariates (BUN, serum albumin concentration, total and direct bilirubin level, AST and ALT level, and presence or absence of ascites) were tested in 207 patients, using 384 levels." (PMID 22547995, 2012). "Variability in preoperative optimization (e.g., albumin and FFP transfusions, paracentesis) may introduce bias, as liver function and ascites control were not uniform across cases." (PMID 40390754, 2025).
type 2 diabetes (529 papers, 2005 to 2026). "The glycated albumin‐to‐haemoglobin A1c (GA/HbA1c) ratio independently predicted mortality in type 2 diabetes, showing a U‐shaped association." (PMID 40590067, 2025). "Cross‐sectional studies of individuals with type 2 diabetes have also found positive associations between eGFR and serum bilirubin levels, and inverse relationships with urinary albumin levels." (PMID 40356408, 2025). "Higher U-TXM was associated with older age, female sex, current smoking, type 2 diabetes, higher body size, urinary albumin/creatinine ratio of ≥3 mg/mmol, and higher estimated glomerular filtration rate." (PMID 38385506, 2024). "This study aimed to explore the association between serum albumin (ALB) levels and diabetic retinopathy in patients with type 2 diabetes." (PMID 38369636, 2024). "PDR progression in patients with type 2 diabetes is associated with baseline renal dysfunction, including elevated serum creatinine, decreased eGFR, and high urine albumin/creatinine ratio." (PMID 38274226, 2023). "Plasma LRG1 level was independently associated with urinary albumin excretion in patients with type 2 diabetes." (PMID 37916147, 2023). "Twenty-four hour ambulatory blood pressure measurement provides an added value to the routine measurement of albumin creatinine ratio in identifying patients with type 2 diabetes at risk of accelerated eGFR decline." (PMID 37576104, 2023). "Poorly controlled type 2 diabetes and obesity are also associated with inflammatory markers like the neutrophil lymphocyte ratio and the C-reactive protein/albumin rate." (PMID 37370958, 2023). "In order to investigate additional functional implications of caveolar loss generated by obesity-related type 2 diabetes (OB-T2D), we analyzed albumin uptake." (PMID 37887297, 2023). "Markers of chronic subclinical inflammation, such as low levels of serum albumin, were associated with an increased risk of type 2 diabetes." (PMID 35290727, 2022). "It was verified that a reduction in urinary albumin level in type 2 diabetes is associated with reno-protective effects." (PMID 34281284, 2021). "In a previous study of hemodialysis patients with type 2 diabetes, the percent glycated albumin showed a positive and independent association with the plasma XOR activity." (PMID 33580173, 2021). "This review recommends that for SCT patients with potential Type 2 diabetes, HbA1c should be used in combination with another diagnostic tool such as fasting blood glucose, fructosamine, or glycated albumin to decrease the chances of a missed diagnosis." (PMID 32923278, 2020). "Baricitinib down-regulates urine CCL2 expression with a decreased urine albumin–creatinine ratio (UACR) in type 2 diabetes patients at high risk for progressive DN in a phase 2 randomized controlled clinical trial." (PMID 32365893, 2020). "In patients with DKD, the NLR was demonstrated to be associated with the 24-h urine protein level and albumin excretion in 80 Turkish patients with newly diagnosed type 2 diabetes." (PMID 32524865, 2020). "Evidences also showed the independent association of FGF21 levels with urinary albumin excretion (UAE) or albuminuria in type 2 diabetic patients." (PMID 31205953, 2019). "In a Japanese study, sleep duration has a U-shaped association with the urinary albumin excretion levels in patients with type 2 diabetes, suggesting that not only short sleep but also long sleep is associated with albuminuria." (PMID 29470498, 2018). "We here evaluated the association of serum levels of glycated albumin (GA) and endogenous secretory receptor for advanced glycation end products (esRAGE) with coronary artery remodeling in type 2 diabetic patients." (PMID 30482197, 2018). "Evaluation of glycated albumin and microalbuminuria as early risk markers of nephropathy in type 2 diabetes mellitus." (PMID 29527102, 2018).
type 2 diabetes (continued). "A previous study reported that short sleep duration and daytime sleepiness was associated with increased 24-h urinary albumin excretion levels in patients with type 2 diabetes." (PMID 29470498, 2018). "Increased serum levels of glycated albumin, cystatin C, and adipokine C1q tumor necrosis factor related protein 1 were associated with poor coronary collateralization in type 2 diabetic patients with stable coronary artery disease and CTO." (PMID 29422093, 2018). "Low serum albumin concentration enhanced the risk for incident type 2 diabetes; however, inverse correlations have been reported as well." (PMID 28430803, 2017). "al. elevated betatrophin levels in type 2 diabetes have been found to be associated with impaired renal function and also with urinary albumin excretion." (PMID 28257453, 2017). "In an independent cohort with manifest type 2 diabetes, the association of suPAR and urinary albumin excretion was conserved at later stages of disease." (PMID 28091558, 2017). "In line with previous studies in type 2 diabetes patients, high levels of sTNFR1 and sTNFR2 were associated with worsened kidney function and higher urinary albumin/creatinine ratio." (PMID 26928194, 2016). "The aim of this study was to investigate if hemoglobin concentration is associated with the degree of change in urinary albumin-creatinine ratio or the development of albuminuria in patients with type 2 diabetes." (PMID 26023923, 2015). "A recent study showed that low dietary magnesium and low mean serum albumin levels were associated with higher risk of type 2 diabetes." (PMID 25072784, 2014). "In conclusion, the current study is the first epidemiological study to demonstrate the presence of a U-shaped association between sleep duration and urinary albumin excretion in patients with type 2 diabetes." (PMID 24265736, 2013). "In this context, we investigated the association between sleep duration and urinary albumin excretion in Japanese type 2 diabetic patients." (PMID 24265736, 2013). "The addition of sE-selectin, serum albumin and leukocyte count improved the accuracy of a risk model for type 2 diabetes compared to a basic model based on sex, BMI and familiy history of type 2 diabetes." (PMID 21674000, 2011). "Blood lead, urine albumin, having type 2 diabetes, and missing teeth were positively associated with urinary Cd concentrations, whereas BMD was inversely associated with urine Cd." (PMID 19479015, 2009). "The present study showed that glycated albumin was an independent risk factor for CAD in patients with type 2 diabetes, with odds ratio being 3.456(95% CI 1.78–6.72, P < 0.001)." (PMID 17178005, 2006). "The glycated albumin‐to‐glycated haemoglobin (GA/HbA1c) ratio is a potential marker of glycaemic variability; however, its association with adverse clinical outcomes in type 2 diabetes remains unclear." (PMID 40590067, 2025). "A cross-sectional study on the global prevalence of microalbuminuria revealed that the prevalence of elevated urinary albumin levels and the risk of kidney disease progression in type 2 diabetes patients in Asia are greater than those in other regions of the world." (PMID 40824899, 2025). "Our study mainly explored whether urinary albumin excretion can be used as a risk factor for fractures in patients with type 2 diabetes." (PMID 39735781, 2024). "In addition, low albumin levels can also be associated with type 2 diabetes, a relevant risk factor for AD." (PMID 38069410, 2023). "We utilize this collagen-binding, serum albumin-fused IL-4 variant (CBD-SA-IL-4) delivered in a hyaluronic acid (HA)-based gel for localized application of IL-4 to dermal wounds in a type 2 diabetic mouse model known for poor healing as proof-of-concept for improved tissue repair." (PMID 37696884, 2023). "Thus, we aimed to evaluate the association of diabetic peripheral neuropathy with urinary albumin excretion in patients with type 2 diabetes using DPN-Check®." (PMID 37373782, 2023).
type 2 diabetes (continued). "Our data suggests that in Chinese patients with type 2 diabetes, low serum albumin may be independently related to the risk of DPN, which may be due to the reduced anti-inflammatory, anti-oxidant and anti-atherosclerotic effects." (PMID 34526116, 2021). "Since reduced albumin has also been associated with the development of type 2 diabetes, the results further suggest that weight gain may be mediating future risk of type 2 diabetes found in prior studies." (PMID 33776937, 2021). "Additionally, glucose can impair FFA binding to albumin, which has been implicated in the progression of type 2 diabetes." (PMID 30266430, 2019). "We hypothesize that genes that influence type 2 diabetes in the UC Davis Zucker rat may have causal effects on urinary albumin excretion and other measures of kidney function or disease." (PMID 29211750, 2017). "Serum albumin concentration is associated with both type 2 diabetes and metabolic syndrome (MetS)." (PMID 28430803, 2017). "Although various causes may bring about hyperglycemia in hospitalized type 2 diabetic patients, our findings suggest that routine screening for retinopathy and urine albumin excretion can be helpful in predicting mortality after discharge." (PMID 28473872, 2017). "Based on the potential antioxidant properties of serum albumin, emerging evidence indicates that serum albumin concentration might be associated with metabolic disorders such as type 2 diabetes and metabolic syndrome (MetS)." (PMID 28430803, 2017). "In addition, the urine albumin excretion rate was an independent factor associated with GFR decline rate in type 2 diabetic patients." (PMID 23349979, 2013). "Similarly, low albumin levels in male patients with type 2 diabetes are a risk factor for OP." (PMID 41041308, 2025). "It was reported that CKD, high urine albumin to creatinine ratio, and low eGFR were associated with DR prevalence among type 2 diabetes mellitus (T2DM) populations." (PMID 40741177, 2025). "Once-daily insulin degludec is another albumin-bound insulin and was shown in double-blind crossover Phase 3 trials to be associated with a reduced rate of overall symptomatic hypoglycaemia during 32 weeks of treatment as compared with once-daily glargine U100 in both type 1 and type 2 diabetes." (PMID 37308751, 2023). "Elevated albumin leakage, measured as 125I-albumin accumulation, has been shown in the eye, sciatic nerve, aorta, and kidney of biobreeding rats (a model of type 2 diabetes) and STZ rats—tissues prone to diabetic vascular injury in humans." (PMID 41511372, 2026). "The urinary albumin:creatinine ratio (uACR) can exhibit significant temporal changes but few studies have characterized transition patterns between uACR categories in type 2 diabetes." (PMID 40303548, 2025). "For this bonus, there are only some exemptions regarding the measurement of albumin for type 2 diabetes and/or CKD patients with creatinine clearance < 25 mL/min, but not for the measurement of creatinine which is required to calculate the UACR." (PMID 40428801, 2025). "This crossover trial compares individual urine albumin-creatinine ratio responses to dapagliflozin therapy, after re-exposure to dapagliflozin, and to placebo among patients with type 2 diabetes and albuminuria." (PMID 40126478, 2025). "A portion of glycated albumin (fructosamine) in healthy persons is 6-13 %, whereas it can reach 30 % in persons with type 2 diabetes." (PMID 41321387, 2025). "Current ADA guideline recommends annual assessment of urinary albumin and eGFR for all individuals with Type 2 diabetes." (PMID 40860624, 2025). "GSK3β-targeted therapeutics have protective effects on urinary albumin excretion in models of both type 1 and type 2 diabetes." (PMID 39880090, 2025). "Participants (n = 1,116) had type 2 diabetes, urine albumin-to-creatinine ratio (UACR) ≥ 300 mg/g, and eGFR 30–89.9 mL/min/1.73 m2." (PMID 40548378, 2025).